SNORA46 (small nucleolar RNA, H/ACA box 46)
Synonyms: ACA46
Gene: Small nucleolar RNA gene on chromosome 16 (58,548,499 to 58,548,633, reverse strand). Ensembl gene ENSG00000207493.
Gene Ontology:
Biological process: RNA processing
Cellular component: nucleolus
Homologues: Orthologues: chimpanzee SNORA46 (100% identical), macaque SNORA46 (99% identical), dog SNORA46 (95% identical), pig SNORA46 (89% identical), guinea pig SNORA46 (87% identical).
Diseases named in the same sentence as SNORA46 in open-access papers:
SNORA46 is named in the same sentence as 5 diseases in open-access papers, as found by Europe PMC text mining. Sharing a sentence is not in itself a finding about the gene and the disease. The quoted sentences say what the papers report.
meningioma (1 paper, 2019). A generally slow growing tumor attached to the dura mater. "When analyzing these genes’ expression across each meningioma grade, we observed how GREM2, SNORA46, and SNORA48 were expressed at significantly higher levels in I NP when compared to I P, secondary or de novo grade II, and grade III." (PMID 31039818, 2019). "In our study, the higher levels of SNORA46 and SNORA48 found in low-grade meningiomas compared to higher-grade tumors point towards their role as cancer or tumor progression suppressors." (PMID 31039818, 2019). "GREM2, SNORA46, and SNORA48 were each expressed at significantly higher levels in grade I meningiomas than grade II and III (p = 0.047, p = 0.017, and p = 0.038, respectively; one-tailed t-test)." (PMID 31039818, 2019). "Among the genes that we have identified as being differentially expressed between grade I and grade II-III tumors are GREM2, SNORA46, and SNORA48, found at higher levels in low grade meningiomas than in higher grade tumors." (PMID 31039818, 2019). "Among the numerous genes differentially expressed across meningioma grades, we identified GREM2, a regulator of the BMP pathway, and the snoRNAs, SNORA46 and SNORA48, as being significantly reduced in meningioma progression by RNA-seq analysis." (PMID 31039818, 2019).
infection (1 paper, 2025). The state of being infected such as from the introduction of a foreign agent such as serum, vaccine, antigenic substance or organism. "In contrast to expression changes induced by Delta infection, RT-qPCR validation of Omicron BA.2-infected cells only identified significant regulation of SNORA62, while expression of SNORA46, SNORD97, and SNORD109B was not significantly altered." (PMID 40510596, 2025).
SNORA46 also shares sentences with these, for which no sentence is quoted: cancer (1 paper); glioblastoma (1); tumor (1).